GRAP (GRB2 related adaptor protein)
Description:
Couples signals from receptor and cytoplasmic tyrosine kinases to the Ras signaling pathway. Plays a role in the inner ear and in hearing.
Synonyms: DFNB114
Tractability: Antibody: UniProt places it where antibodies can reach, with medium confidence; its Gene Ontology location is reachable by antibodies, with medium confidence. PROTAC: ubiquitination databases record sites on it.
Gene: Protein-coding gene on chromosome 17 (19,020,656 to 19,047,143, reverse strand). Ensembl gene ENSG00000154016.
Subcellular location: Membrane; Synapse
Subcellular location (Human Protein Atlas): Centrosome
Pathways (Reactome):
Signal Transduction: Signaling by SCF-KIT
Gene Ontology:
Molecular function: protein binding; epidermal growth factor receptor binding; phosphotyrosine residue binding
Biological process: sensory perception of sound; cell-cell signaling; Ras protein signal transduction; regulation of MAPK cascade; signal transduction
Cellular component: COP9 signalosome; cytoplasm; cytosol; membrane; nucleoplasm; plasma membrane; presynapse; synapse
Genetic constraint (gnomAD): Loss-of-function variants: 4 observed, 6.71 expected, observed/expected ratio (o/e) 0.6, 90% interval 0.29 to 1.35. That is too few expected variants to judge how well the gene tolerates losing a copy. Missense variants: 108 observed, 136.2 expected, observed/expected ratio (o/e) 0.79, 90% interval 0.68 to 0.93. Synonymous variants: 67 observed, 58.18 expected, observed/expected ratio (o/e) 1.15, 90% interval 0.94 to 1.41.
Gene-disease validity (ClinGen):
ClinGen rates the evidence that GRAP causes each of these diseases.
nonsyndromic genetic hearing loss (autosomal recessive): Limited. A disease characterized by hearing loss that is not part of a larger syndrome.
Homologues: Orthologues: mouse Grap (92% identical), rat Grap (90% identical), tropical clawed frog grap (67% identical), zebrafish grapa (60% identical), zebrafish grapb (59% identical), chimpanzee GRAPL (46% identical), Caenorhabditis elegans nck-1 (27% identical), Drosophila melanogaster dock (26% identical). Paralogues in human: GRB2 (59% identical), GRAP2 (48% identical), GRAPL (47% identical), NCK1 (29% identical), NCK2 (29% identical), SLA2 (24% identical), SH2D5 (22% identical), DAPP1 (21% identical), SLA (20% identical).
Diseases named in the same sentence as GRAP in open-access papers:
GRAP is named in the same sentence as 8 diseases in open-access papers, as found by Europe PMC text mining. Sharing a sentence is not in itself a finding about the gene and the disease. The quoted sentences say what the papers report.
prostate carcinoma (2 papers, 2018 to 2020). A carcinoma that arises from epithelial cells of the prostate gland. "EPSTI1 for breast cancer, AR for prostate cancer, GRAP for oral squamous cell carcinoma, CDCP1 and PLAGL2 for ovarian cancer were the only five direct targets identified for miR‐654‐5p thus far." (PMID 33135351, 2020). "miR-654-5p has been reported to promote carcinoma proliferation in oral squamous cell through the miR-654-5p/GRAP/Ras/Erk signalling pathway, and down-regulation of miR-654-5p inhibited the proliferation of prostate cancer cells." (PMID 30306067, 2018).
deafness (1 paper, 2018). An inherited or acquired condition characterized by the complete loss of the ability to hear from one or both ears. "After ossicle removal, opening of the cochlea via cochleostomy, and electrode insertion into the medial turn of the cochlea for 1 or 7 d resulting in acute deafness of the left ear of hearing rats, no changes in expression of Fos protein, fos mRNA, GRAP, or IBA1 were observed." (PMID 29520220, 2018).
cancer (3 papers, 2017 to 2020). A tumor composed of atypical neoplastic, often pleomorphic cells that invade other tissues. "Other candidates, such as CD79B, MAP4K1, GRAP, TNFRSF13C, and INA, had comparable scores and are candidates for further study, as they have also been implicated in carcinogenesis of other cancer types." (PMID 28146432, 2017). "SAM68 could interact with GRAP to active oncogenic pathways, such as epidermal growth factor and PI3K/Akt signaling pathways, thereby contributing to cancer progressing." (PMID 33028275, 2020).
GRAP also shares sentences with these, for which no sentence is quoted: breast carcinoma (1 paper); glioma (1); oral squamous cell carcinoma (1); ovarian carcinoma (1); tumor (1).